ST3GAL1 (ST3 beta-galactoside alpha-2,3-sialyltransferase 1)
Diseases named in the same sentence as ST3GAL1 in open-access papers (continued):
Sharing a sentence is not in itself a finding about the gene and the disease.
meningioma (2 papers, 2021 to 2024). A generally slow growing tumor attached to the dura mater. "In the malignant meningioma cell line, we observed changes in expression of sialyltransferases (ST3GAL1/2/3, ST6GALNAC5, and ST8SIA1) after glycation, which correlates with less aggressive behavior." (PMID 34943806, 2021). "High expression of ST3GAL1 and ST3GAL3 in malignant meningiomas may play an essential role in the progression and invasion of this malignancy." (PMID 38274327, 2024). "In the GEO database, mRNA expression of ST3GAL4 was significantly decreased in grade II and III meningiomas (P < 0.05), while the others (ST3GAL1, ST3GAL3, ST3GAL6, ST6GAL1, and ST6GALNAc1) were not." (PMID 38274327, 2024).
ovarian tumor (2 papers, 2016 to 2017). "The St3gal1 gene, encoding a glycosyltransferase, was upregulated by E2 and altered (mostly amplified or showing mRNA upregulation) in 30 % of ovarian tumors." (PMID 26879975, 2016).
serous ovarian cancer (2 papers, 2018 to 2022). "Sialyltransferase ST3Gal1 increases α2,3-sialylation in serous ovarian cancer, promotes EMT and confers paclitaxel resistance." (PMID 36231102, 2022). "In tissue samples, we found that a higher number of patients had a high expression of ST3GAL1 in serous ovarian cancer compared with mucinous, clear cell, and endometrioid ovarian cancer." (PMID 30375371, 2018).
Alzheimer disease (1 paper, 2024). A progressive, neurodegenerative disease characterized by loss of function and death of nerve cells in several areas of the brain leading to loss of cognitive function such as memory and language. "Four SNPs are mapped to FBLN2, ADAM 10, NHSL1, and ST3GAL1 genes previously associated with Alzheimer Disease." (PMID 38291454, 2024).
Arthritis (1 paper, 2016). Inflammation of a joint. "Higher monocyte ST3Gal-1/Neu3 ratios were noted in the arthritis subgroup than those in the no-arthritis subgroup." (PMID 26981635, 2016).
benign bladder tumors (1 paper, 2018). "In a previous work, we have shown that the mRNA of ST3GAL1 was overexpressed in NMIBC but not in muscle invasive BC or in benign bladder tumors and ST3GAL1 plays the major role in the sialylation of the T antigen in BC." (PMID 29454317, 2018).
bipolar disorder (1 paper, 2013). A disorder of the brain that causes unusual shifts in mood, energy, activity levels and the ability to carry out day-to-day tasks. "The third signal in the current study, the negative symptoms-associated genetic variants of the ST3GAL1 gene were also reported to be risk variants for bipolar disorder (BP) in a number of previous reports." (PMID 23382809, 2013).
cervical cancer (1 paper, 2018). A primary or metastatic malignant neoplasm involving the cervix. "Moreover, it was found that high expression of ST6GAL1 was associated with more invasive properties of cervical cancer and that the reduced expression of ST3GAL1, ST3GAL3, and ST3GAL4 may also contribute to the characteristics of cervical cancer." (PMID 30375371, 2018).
clear cell renal cell carcinoma (1 paper, 2015). "However, little is known about prognostic significance of ST3GAL-1 in clear cell renal cell carcinoma (ccRCC)." (PMID 26552809, 2015).
diabetes (1 paper, 2018). "In mouse models of diabetes, the KO of GM3 synthase (ST3GAL1) prevents the diabetes-associated inhibition of wound healing." (PMID 29462882, 2018).
gynecologic cancers (1 paper, 2025). "Among these, ST3 beta‐galactoside alpha‐2,3‐sialyltransferase 1 (ST3Gal1) is a key α2,3‐sialyltransferase (α2,3‐ST) that modifies terminal galactose residues on glycoproteins, and its overexpression has been linked to tumor progression and chemoresistance in gynecologic cancers." (PMID 40497576, 2025).
intestinal infection (1 paper, 2023). "Apart from matching mRNA and protein levels of ST3GAL1 after intestinal infection of mice, we determined the localisation of ST3GAL1 in the infected tissue and furthermore, at the cellular level." (PMID 37848994, 2023).
invasive breast ductal carcinoma (1 paper, 2018). "Additionally, ST3GAL1 can be hypomethylated leading to transcriptional activation in invasive breast ductal carcinoma; this gene was overexpressed in MDA-MB-231 cells in the current study." (PMID 29847599, 2018).
liver cancer (1 paper, 2026). An epithelial or non-epithelial malignant neoplasm that arises from the liver. "Silencing ST3GAL1 significantly reduced Siglec-7 ligand expression on liver cancer cells, enhancing their susceptibility to NK-mediated cytotoxicity and cetuximab-induced antibody-dependent cellular cytotoxicity (ADCC) in epidermal growth factor receptor (EGFR)-expressing tumor cells." (PMID 41961075, 2026).
lupus (1 paper, 2016). "Taken together, these findings suggest that the ST3Gal-1 and Neu3 enzymes in B cells are potential marers of lupus activity." (PMID 26981635, 2016). "Fifth, high ST3Gal-1 and Neu3 levels of PMN cells and monocytes were possible indicators of the presence of lupus proteinuria and a high SLEDAI score." (PMID 26981635, 2016).
malignant meningiomas (1 paper, 2024). "In contrast, ST3GAL1 and ST3GAL3 were highly expressed in the malignant meningioma—HKBMM and IOMM-Lee." (PMID 38274327, 2024).
metastatic melanoma (1 paper, 2020). A melanoma that has spread from its primary site to another anatomic site. "Accordingly, western blot analysis showed that ST3GAL1 was expressed at various levels in metastatic melanoma cell lines, but barely present in normal human epidermal melanocytes (NHEM)." (PMID 33203881, 2020). "To identify putative mediators of ST3GAL1 in metastatic melanoma cells, we performed proteomic analysis of sialylated proteins." (PMID 33203881, 2020).
neuroblastoma (1 paper, 2025). Neuroblastoma (NB) is the most common solid, extracranial childhood tumor. "In our study, ST3GAL1 downregulation was associated with worse outcomes in neuroblastoma patients." (PMID 39860532, 2025).
osteosarcoma (1 paper, 2024). A usually aggressive malignant bone-forming mesenchymal neoplasm, predominantly affecting adolescents and young adults. "In addition, survival analysis showed that only ST3GAL1 was associated with shorter OS and RFS in osteosarcoma, but its prognostic value was not as significant as ST3GAL4." (PMID 38212768, 2024).
prostate tumours (1 paper, 2024). "Here, we determine that expression of the sialyltransferase ST3Gal1 negatively correlates with AR signalling in prostate tumours." (PMID 38448753, 2024). "Taken together, we show that ST3GAL1 is inversely correlated with AR signalling in prostate tumours and is upregulated in CRPC." (PMID 38448753, 2024). "First, we profiled expression of ST3Gal1 in PC and found protein levels to be significantly increased in prostate tumour tissue compared with healthy normal prostatic tissue." (PMID 38448753, 2024). "We report that ST3 beta-galactoside alpha-2,3-sialyltransferase 1 (ST3Gal1) levels negatively correlate with androgen signalling in prostate tumours." (PMID 38448753, 2024). "In the same study, matched paracancerous tissue from patients pre- and post-enzalutamide treatment showed no significant increase in ST3GAL1 levels following treatment, suggesting that the observed increase in ST3GAL1 is specific to prostate tumours." (PMID 38448753, 2024).
renal carcinoma (1 paper, 2022). A carcinoma arising from the epithelium of the renal parenchyma or the renal pelvis. "Previous studies revealed that ST3GAL1 may account for sialylation of EGFR in renal cancer cells, while ST3GAL6 may promote sialylation of EGFR in HeLa cells." (PMID 36092699, 2022).
renal cell carcinoma (1 paper, 2021). "On the other hand, in renal cell carcinoma (RCC) cells ST3GAL1 is positively regulated by MEG3, a lncRNA with a tumor suppressor activity." (PMID 33921986, 2021).
triple-negative breast carcinoma (1 paper, 2022). An invasive breast carcinoma which is negative for expression of estrogen receptor (ER), progesterone receptor (PR), and human epidermal growth factor receptor 2 (HER2). "In addition to ST3GAL1, the elevated levels of ST3GAL2 and its product sialyl-glycolipid stage-specific embryonic antigen 4 (SSEA4) were suggested for the increased chemoresistance of triple-negative breast cancer to genotoxic agents." (PMID 36092699, 2022).
viral infection (1 paper, 2021). "Interestingly, at 48 h p.i., only pneumococcal colonization results in increased St3gal1 expression, indicating that it is an ISG stimulated by bacterial but not viral infection." (PMID 33593970, 2021).
tumor (43 papers, 2009 to 2026). "RT-qPCR of both in vitro and in vivo tumor cells also revealed significant up-regulation of key enzymes involved in glycosphingolipid biosynthesis, including St3gal1, St3gal2, B4galt5, Sptlc2, and Ugcg, in A159V-mutated cells." (PMID 41160695, 2025). "In pancreatic cancer, ST3GAL1 enhances metastatic potential and promotes the synthesis of ligands for Siglec-7 and Siglec-9 on tumour cells to drive tumour-associated macrophage differentiation." (PMID 36077781, 2022). "ST3GAL1 has been implicated in transforming tumor-associated macrophage differentiation to a more suppressive phenotype." (PMID 36605200, 2022). "Members of this family are involved in the synthesis of gangliosides (ST3Gal2 and 5), and the tumor-associated sialyl-T (ST) (ST3Gal1) and sialyl-Lewis (ST3Gal3, 4, and 6) antigens." (PMID 34975914, 2021). "We next set out to test the hypothesis that ST3Gal1 and its associated sialoglycan patterns interact with the immune system to dampen anti-tumour immunity by selectively depleting key components of the immune system." (PMID 38448753, 2024). "Several studies have elucidated the association of ST3GAL-1 with tumor progression." (PMID 26552809, 2015). "Thus, it is conceivable that elevated sLex/a antigen synthesis caused by ST3Gal-1 in the tumor favors tumor cells to bind to selectins and then extricate from the primary tumor enter into blood stream and promote metastasis formation." (PMID 26552809, 2015). "The interaction between GCNT3 and ST3GAL1 further reveals the complex regulatory mechanisms of O-glycosylation and sialylation in tumor progression." (PMID 40352586, 2025). "ST3GAL1 is a membrane protein with sialyl-transferase activity, which has been reported to promote tumor metastasis and invasion by previous study." (PMID 38451187, 2024). "GSEA in 250 patients stratified based on ST3GAL1 gene expression levels revealed 11 gene sets negatively enriched in ST3GAL1high tumours." (PMID 38448753, 2024). "We demonstrate that ST3Gal1 plays an important role in modulating tumour immune evasion through the synthesises of sialoglycans with the capacity to engage the Siglec-7 and Siglec-9 immunoreceptors preventing immune clearance of cancer cells." (PMID 38448753, 2024). "St3gal1 mRNA levels in enzalutamide treated TRAMP-C2 allografts were significantly upregulated compared with vehicle treated tumours." (PMID 38448753, 2024). "Using in vivo models, we have implicated the ST3Gal1-sialoglycan-Siglec axis in macrophage anti-tumour biology and provide proof-of-concept data suggesting that depleting ST3Gal1 associated sialoglycans or targeting their respective Siglecs may boost immune tumour clearance." (PMID 38448753, 2024). "In transcriptomic data from 138 CRPC tumours, levels of ST3GAL1 gene expression were negatively correlated with AR, KLK3, NKX3." (PMID 38448753, 2024). "Given that ST3GAL1 expression is high in tumours which have low levels of androgen signalling we sought to validate this finding using in vitro models." (PMID 38448753, 2024). "We noted that the HALLMARK ANDROGEN RESPONSE gene set was negatively enriched in tumours with high expression of ST3GAL1." (PMID 38448753, 2024). "When comparing the mRNA level of the ST3GAL family in public microarray data from CNS tumors and normal tissue, ST3GAL1, 2, 4, and 5 were found to have lower expressions in the tumor samples compared to normal tissue." (PMID 38067186, 2023). "The overexpression of ST3GAL1 promotes tumorigenesis and is strongly related to the increased tumor grade in BC." (PMID 35444644, 2022). "ST3GAL1-mediated O-linked sialylation of CD55 promoted immune evasion of BC, and ST3GAL1 was overexpressed in high tumor grade." (PMID 35444644, 2022). "The results showed that ST3GAL1, 2, and 6 were consistently and significantly downregulated in tumor tissues, compared with normal samples." (PMID 36092699, 2022).
tumor (continued). "This work provides evidence that ST3GAL1 sustains self-renewal in vitro and tumor growth of glioma-propagating cells (GPCs), promoting the expression of the neurodevelopmental factors OLIG2, SALL2 and SOX2." (PMID 33921986, 2021). "ST3GAL1 has been reported to mainly catalyse the sialylation of the T-antigen, a short O-glycan product often increased in tumour, in agreement with our results with glycosylation inhibitors." (PMID 33627655, 2021). "Treatment with paclitaxel reduced the tumor volume in mice but to a lesser extent in tumors overexpressing ST3GAL1." (PMID 30375371, 2018). "NMIBC expresses two tumor-associated O-linked carbohydrates: the disaccharide (Galβ1,3GalNAc) Thomsen-Friedenreich (T) antigen, and its sialylated counterpart (Siaα2,3Galβ1,3GalNAc) sialyl-T (sT), synthesized by sialyltransferase ST3GAL1, whose roles in BCG response are unknown." (PMID 29454317, 2018). "To conclude, overexpression of ST3GAL1 reduces the curative effect of paclitaxel on tumor growth in nude mice." (PMID 30375371, 2018). "Increasing studies have revealed that the abnormal activity of ST3GAL-1 contributes to the tumor progression." (PMID 26552809, 2015). "Targeting ST3GAL1 may represent a promising strategy to enhance NK cell-mediated anti-tumor immunity in HCC." (PMID 41961075, 2026). "ST3GAL1 can control chimeric antigen receptor (CAR)-T-cell migration to target tumor sites." (PMID 41453319, 2025). "We next determined the effects of St3gal1 on tumour growth in a syngeneic allograft model of PC." (PMID 38448753, 2024). "For example, ST3GAL1 could be a promising therapeutic target in melanoma owing to its role in promoting tumor metastasis." (PMID 36172374, 2022). "Overexpression of ST3Gal1 has been shown to promote tumor cell migration and metastasis, which may involve epidermal growth factor receptor (EGFR) signaling, or receptor tyrosine kinase AXL dimerization/activation." (PMID 34975914, 2021). "ST3GAL1 has been shown to exert a tumor promoting effect in a PyMT mouse model of breast cancer." (PMID 33203881, 2020). "It has also been confirmed that abnormal ST3GAL-1 activities could involve in malignant cell transformation and tumor progression." (PMID 26552809, 2015). "Finally, we measured the levels of St3Gal1, St6Gal1, and St6GalNac3 in the tumor explants." (PMID 39104719, 2024). "Our study also provides compelling evidence that ST3Gal1 regulates VEGF‐A expression and function, thereby promoting angiogenesis and tumor invasion." (PMID 40497576, 2025). "The violin plots demonstrate that genes including CTNV, FIB, GAB2, LAMP3, ST3GAL1 and ST3GAL5 exhibit distinct expression profiles, with tumour tissues showing markedly different expression distributions compared to normal controls." (PMID 41362116, 2025). "This study investigates the therapeutic potential of targeting the ST3Gal1/VEGF‐A axis to overcome angiogenic resistance and suppress tumor progression in EC." (PMID 40497576, 2025). "ST3GAL1 is also a transcriptional target of TGF-β1, suggesting a self-sustaining feedback loop promoting tumor vascularization." (PMID 40885395, 2025). "In PDAC, upregulation of ST3GAL1 and ST3GAL4 in tumor cells was identified as the main contributor to the synthesis of Siglec-7 and Siglec-9 ligands." (PMID 40885395, 2025). "ST3GAL1 gene can promote immune escape of tumor cells by targeting CD55 gene, and can promote tumor angiogenesis and disease progression." (PMID 39711442, 2024). "We identified the expression of the α2,3 sialyltransferases ST3GAL1 and ST3GAL4 as main contributor to the synthesis of ligands for Siglec-7 and Siglec-9 in tumour cells." (PMID 33627655, 2021). "Authors identified ST3GAL1 and ST3GAL4 as the main contributors to the synthesis of ligands for Siglec-7 and Siglec-9 in tumor cells." (PMID 33921986, 2021).
tumor (continued). "In contrast, βII-spectrin, a cytoskeletal molecule expressed on CAR-T cells, enhances the tumour specificity of CAR-T cells to localize to the tumour site and is able to reverse ST3GAL1-mediated non-specific T-cell migration, thereby inhibiting tumour growth in mice." (PMID 39070147, 2024). "In summary, we report that ST3Gal1 synthesises Siglec-7 and Siglec-9 ligands which are critical to maintaining immune suppression in the prostate TIME and that targeting this axis may reactivate anti-tumour immunity." (PMID 38448753, 2024). "When mice containing St3gal1-/- TRAMP-C2 cells were culled and harvested at day 47 there were no signs of early tumour formation." (PMID 38448753, 2024).